PRICKLE2 (prickle planar cell polarity protein 2)
Description:
Is involved in the organization and maintenance of axon initial segment (AIS) architecture, likely cooperating with IGSF9B to regulate ANK3/ANKG localization to AIS (By similarity). By binding to and regulating ANK3/ANKG, it modulates its ability to bundle microtubules, a crucial mechanism for establishing neuronal polarity and AIS formation (By similarity). During early embryonic development, has a role in blastocyst formation, likely controlling the redistribution of the microtubule network during embryo compaction and the establishment of apical/basal cell polarity (By similarity).
Synonyms: DKFZp686D143; EPM5
Tractability: PROTAC: ubiquitination databases record sites on it; its protein half-life has been measured.
Gene: Protein-coding gene on chromosome 3 (64,092,236 to 64,445,476, reverse strand). Ensembl gene ENSG00000163637.
Subcellular location: Postsynaptic density; Cell projection, axon; Cell projection, dendrite; Nucleus
Subcellular location (Human Protein Atlas): Golgi apparatus; Vesicles
Gene Ontology:
Molecular function: zinc ion binding
Biological process: blastocyst formation; protein localization to axon; Wnt signaling pathway, planar cell polarity pathway
Cellular component: cytoplasm; axon; axon initial segment; dendrite; nucleus; postsynaptic density
Genetic constraint (gnomAD): Loss-of-function variants: 19 observed, 82.12 expected, observed/expected ratio (o/e) 0.23, 90% interval 0.16 to 0.34. The upper end of that interval is the gene's LOEUF score, 0.34, which puts it in group 1 of 6, group 1 being the genes least tolerant of losing a copy. Missense variants: 929 observed, 1,144.9 expected, observed/expected ratio (o/e) 0.81, 90% interval 0.77 to 0.86. Synonymous variants: 450 observed, 438.73 expected, observed/expected ratio (o/e) 1.03, 90% interval 0.95 to 1.11.
Gene-disease validity (ClinGen):
ClinGen rates the evidence that PRICKLE2 causes each of these diseases.
complex neurodevelopmental disorder (autosomal dominant): Limited. A disorder that involves more than one phenotype associated with the central nervous system, including but not limited to intellectual disability, autism, and seizures (epilepsy).
Homologues: Orthologues: chimpanzee PRICKLE2 (99% identical), macaque PRICKLE2 (99% identical), pig PRICKLE2 (97% identical), rabbit PRICKLE2 (96% identical), dog PRICKLE2 (96% identical), mouse Prickle2 (95% identical), rat Prickle2 (95% identical), guinea pig PRICKLE2 (94% identical), tropical clawed frog prickle2 (79% identical), zebrafish prickle2b (67% identical), zebrafish prickle2a (55% identical), Drosophila melanogaster pk (35% identical), and 2 more. Paralogues in human: PRICKLE3 (35% identical).
Diseases named in the same sentence as PRICKLE2 in open-access papers:
PRICKLE2 is named in the same sentence as 16 diseases in open-access papers, as found by Europe PMC text mining. Sharing a sentence is not in itself a finding about the gene and the disease. The quoted sentences say what the papers report.
epilepsy (4 papers, 2016 to 2022). A brain disorder characterized by episodes of abnormally increased neuronal discharge resulting in transient episodes of sensory or motor neurological dysfunction, or psychic dysfunction. "Among the risk factors for ASD, Prickle2 has been identified in genetic studies of ASD subjects with epilepsy." (PMID 32641624, 2020). "Both epilepsy and ASD are also reported in patients with PRICKLE2 mutations, while Prickle2 knockout mice display a lower threshold for seizures and ASD-like behaviors." (PMID 36083912, 2022). "Knockdown studies demonstrated that Prickle2 and its partner, Igsf9b, are involved in positioning of the axon initial segment (AIS), where many ASD and epilepsy susceptibility proteins accumulate." (PMID 32641624, 2020). "The molecular mechanism by which Prickle2 underlies AIS dysregulation provides a positive clue for understanding shared pathogenic signaling between ASD and epilepsy." (PMID 32641624, 2020). "A chromosomal microdeletion encompassing Prickle2 is associated with ASD and epilepsy." (PMID 32641624, 2020). "Since these phenotypes are due to a reduced expression of the wild-type Prickle2 protein, the degradation of Prickle2 might be a reasonable target for development of therapeutic and preventive strategies to treat human epilepsy and ASD." (PMID 30814664, 2019). "Prickle2 has been identified in genetic studies of subjects with autism spectrum disorder (ASD) and epilepsy, but the pathological mechanism of Prickle2 remains to be fully understood." (PMID 32641624, 2020). "The novel function of Prickle2 in AIS cytoarchitecture provides new insights into the shared pathology of ASD and epilepsy." (PMID 32641624, 2020). "The molecular basis of some Prickle2-related neuronal deficits and their relation with pathology such as ASD and epilepsy could therefore be revisited on the basis of these results." (PMID 36083912, 2022).
autism (2 papers, 2019 to 2020). Persistent deficits in social interaction and communication and interaction as well as a markedly restricted repertoire of activity and interest as well as repetitive patterns of behavior. "For example, deletion of Prickle2 causes a lower seizure threshold and autism-like behaviors with hippocampal synaptic abnormalities." (PMID 33015060, 2020). "It has been reported that Prickle2 deficiency reduced neurite outgrowth levels in mouse N2a cells and led to autism-like behaviors and hippocampal synaptic dysfunction in mice." (PMID 33015060, 2020). "Interestingly, mice lacking the Prickle2 gene show an abnormal behaviour similar to human autism." (PMID 30814664, 2019).
breast carcinoma (2 papers, 2023 to 2025). "(−)-Sativan, a Spatholobus suberectus-derived isoflavane, suppresses the proliferation of breast cancer cells by upregulating miR-200c-3p to downregulate its direct target, such as prickle planar cell polarity protein 2 (PRICKLE2; EPM5)." (PMID 36612314, 2023). "Using this capability, we detected and validated three genes—PCDHA10, PRICKLE2, and PRTG—demonstrating their inhibiting effects on cancer cell growth and migration in breast cancer cell lines." (PMID 40581983, 2025). "Through model interpretation and biological experimental validation, we identified three novel breast cancer genes—PCDHA10, PRICKLE2, and PRTG—demonstrating their inhibitory effects on cell proliferation and migration in breast cancer cell lines." (PMID 40581983, 2025). "Using cfMethylPre, we identified and validated three novel genes—PCDHA10, PRICKLE2, and PRTG—that exhibit inhibitory effects on breast cancer cell proliferation and migration, highlighting its potential in precision oncology." (PMID 40581983, 2025). "Furthermore, its interpretability enables the identification of critical cancer-associated genes, with experimental validation uncovering three novel genes—PCDHA10, PRICKLE2, and PRTG—that exhibit inhibitory effects on breast cancer cell proliferation and migration." (PMID 40581983, 2025).
amyloid (1 paper, 2020). "The results of thioflavin S (ThioS) staining showed that Prickle2-overexpressed 3 × Tg mice displayed fewer mature amyloid plaques than vehicle-treated 3 × Tg mice." (PMID 33015060, 2020).
cognitive deficits (1 paper, 2020). "Intravenous injection of Prickle2-overexpressing AAV-PHP.eB vectors improved the cognitive deficits in 3xTg mice." (PMID 33015060, 2020). "The data demonstrated that overexpression of Prickle2 could improve cognitive deficits in 3 × Tg mice." (PMID 33015060, 2020).
gastric cancer (1 paper, 2022). A primary or metastatic malignant neoplasm involving the stomach. "Few studies have focused on the biological functions of PRICKLE2, PDE12, RBP1, THSD7B, and TUBB6 in gastric cancer." (PMID 36226177, 2022).
lung adenocarcinoma (1 paper, 2023). A carcinoma that arises from the lung and is characterized by the presence of malignant glandular epithelial cells. "In patients with lung adenocarcinoma (LUAD), a subtype of NSCLC, miR-665 can enhance the malignancy of cells by binding to Prickle Planar Cell Polarity Protein 2 (PRICKLE2)." (PMID 37894282, 2023).
nasal polyps (1 paper, 2023). "Our study also revealed decreased immunohistochemical expressions of the PCP proteins, Dishevelled-1, Dishevelled-3, Frizzled3, Frizzled6, Prickle2 and Vangl2 in the nasal polyp compared to the turbinate mucosa." (PMID 38232516, 2023). "Immunohistochemical expressions of the PCP proteins, Dishevelled-1, Dishevelled-3, Frizzled3, Frizzled6, Prickle2 and Vangl2 were lower in the nasal polyps than in the turbinate mucosae." (PMID 38232516, 2023). "Immunohistochemical expressions of Dishevelled-1, Dishevelled-3, Frizzled3, Frizzled6, Prickle2 and Vangl2 were lower in the nasal polyps than in the turbinates." (PMID 38232516, 2023). "In addition, we showed decreased immunohistochemical expression of Prickle2 and Vangl2 in nasal polyps, and this may also contribute to PCP disarrangement in this tissue." (PMID 38232516, 2023).
cancer (5 papers, 2014 to 2025). A tumor composed of atypical neoplastic, often pleomorphic cells that invade other tissues. "DACT1, VRK2, MELTF, and FGF12 have been implicated in cancers other than CC, and PRICKLE2 has been reported to correlate with CC." (PMID 32408396, 2020). "In addition, Prickle2 and Cacna2d3 are two potential tumor suppressor genes in the development and progression of carcinoma." (PMID 32245399, 2020).
tumor (3 papers, 2018 to 2022). "Therefore, these target genes can also provide new directions for future tumor treatment, especially the five genes DLC1, LRFN5, NOVA1, POU3F2 and PRICKLE2 which were positively related to the overall survival time." (PMID 35578189, 2022). "In fact, mutations within the PC, PRICKLE2 and TSC2 genes have previously been associated with non-neurodegenerative diseases including diseases involved in energy deficiency, tumour formation and seizures." (PMID 32019516, 2020).
psychiatric diseases (1 paper, 2020). "Here, because Igsf9 family proteins are associated with psychiatric diseases and seizures, we studied the physiological interaction between Prickle2 and Igsf9b." (PMID 32641624, 2020).
PRICKLE2 also shares sentences with these, for which no sentence is quoted: autism spectrum disorder (2 papers); neurodegenerative disease (2); Alzheimer disease (1); schizophrenia (1); tauopathy (1).